MIR125A (microRNA 125a)
Synonyms: hsa-mir-125a; MIRN125A; miRNA125A; mir-125a
Gene: MicroRNA gene on chromosome 19 (51,693,254 to 51,693,339, forward strand). Ensembl gene ENSG00000208008.
Gene Ontology:
Biological process: miRNA-mediated post-transcriptional gene silencing
Cellular component: RISC complex
Homologues: Orthologues: chimpanzee ptr-mir-125a (99% identical), macaque mml-mir-125a (99% identical), rat Mir125a (92% identical), pig ssc-mir-125a (87% identical), guinea pig MIR125A (78% identical), mouse Mir125a (77% identical), zebrafish mir125b-3 (62% identical). Paralogues in human: MIR125B2 (63% identical), MIR125B1 (62% identical), MIR99A (48% identical), MIR10A (45% identical), MIR100 (43% identical), MIR99B (43% identical), MIR10B (41% identical).